TLR4 (toll like receptor 4)
Diseases named in the same sentence as TLR4 in open-access papers (continued):
Sharing a sentence is not in itself a finding about the gene and the disease.
cancer (continued). "NF-κB signaling pathway and MAPK signaling pathway are two known TLR4 downstream pathways and two important pathways in cancer cachexia." (PMID 34867338, 2021). "There is also a report that paclitaxel can promote metastases in some cancers through TLR4 signaling." (PMID 33554122, 2021). "To study the key roles of TLR4 signalling in cancer progression and metastasis, we next established different cellular models in which cell behaviour is under optical control." (PMID 34502140, 2021). "Previous studies have revealed the relationship between toll-like receptor 4 (TLR4) polymorphisms and cancer susceptibility." (PMID 34631699, 2021). "Among these receptors, TLR4 is the most extensively studied TLR which is known to mediate the innate immune response in inflammatory disorders such as cancers." (PMID 34904014, 2021). "HMGB1 can bind to Toll-like receptor 4 (TLR4), promote the release of proinflammatory cytokines from monocytes/macrophages and regulate the function of endothelial and cancer cells." (PMID 34588987, 2021). "We also examined the levels of active NF-κB and AKT, which are also TLR4 effectors and often activated in skeletal muscle of cancer patients." (PMID 34950660, 2021). "This plant, with a strong cytotoxic effect on cancer cells as well as increased apoptosis and its effect on molecules involved in TLR4 signaling as the immunomodulatory effect can be a suitable candidate for in-vivo studies in the future for cancer therapy." (PMID 34904014, 2021). "In this work we discovered that in cancer cells expressing TLR4, HMGB1 can induce TGF-β production and secretion." (PMID 34234778, 2021). "Differential expression of TLR4 between cancer cells and normal tissues existed in many types of cancer." (PMID 34631699, 2021). "Cancer cells expressing TLR4 release TGF-β in response to stimulation with HMGB1 followed by TGF-β-induced upregulation of galectin-9 expression, forming such an HMBG1-triggered autocrine loop." (PMID 34234778, 2021). "Lipopolysaccharide (LPS), a TLR4 agonist, can induce anti-inflammatory cytokine secretion (e.g., IL-8) by activating TLR4 expressed in cancer cells." (PMID 34141706, 2021). "Knockout of TLR4 completely abolished the HFD-enhanced CRC growth by re-programming the cancer metabolism and reducing ATP production." (PMID 34385421, 2021). "For instance, it has been shown that lipopolysaccharide (LPS)-induced TLR4 signaling promotes cancer cell proliferation and contributes to cancer development and progression in ESCC." (PMID 34926275, 2021). "In particular, it has been demonstrated that either chemotherapy or radiotherapy lead to HMGB1 release from dying cancer cells, promoting antigen processing and presentation on dendritic cells (DCs) through TLR4-MyD88 axis." (PMID 33540645, 2021). "Immunochemistry staining further verified that TLR4 was overexpressed in PDAC cancer cells when compared to adjacent pancreatic ductal cells." (PMID 34718325, 2021). "Taken together, these data suggest that TLR4 regulates the CRC growth under HFD by programming the cancer metabolism." (PMID 34385421, 2021). "TLR4 and its adaptor MyD88 have been reported as oncogenic signaling in several human cancers, including HCC." (PMID 33195243, 2020). "Of note, miR-365 was indicated to target TLR4 and thereby suppressed cancer progression and increased hemoglobin content." (PMID 33292210, 2020). "It has been reported in the literature that TLR4 promotes the occurrence of cancer by regulating the expression of the downstream protein interferon regulatory factor 3 (IRF3)." (PMID 33292210, 2020). "Coley's toxin (a mixture of inactivated Streptococcus pyogenes and Serratia marcescens) and BCG (Bacillus Calmette-Guerin), a TLR2 and TLR4 agonist have been used as a drug for long-term cancer treatment." (PMID 33469538, 2020).
cancer (continued). "Other studies highlighted that TLR-4 increased the rate of lung metastasis in inflamed mice through the upregulation of C–C chemokine receptor type 2 (CCR2) expression and proved that the TLR4/Myd88/NF-κB/MMP2 axis plays a crucial role in cancer metastasis." (PMID 32367494, 2020). "For instance, the extra domain A (EDA) of fibronectin, a matrix protein, can bind to TLR-4 upon proteolytic cleavage and has showed some promises as adjuvant in cancer vaccines in pre-clinical models." (PMID 32117911, 2020). "The lung senses distant cancer cells and then secretes an abundant amount of S100A8/A9, which in turn attracts distant cancer cells through their surface TLR4." (PMID 32490214, 2020). "TLR4, which is detected not only in immune cells but also in numerous cancers, has been verified as an important medium that links inflammation and tumorigenesis." (PMID 32095158, 2020). "Several studies have demonstrated that the expression of TLR4 is increased in various cancer cells and tissues, including gastrointestinal cancers, hepatic cancer, pancreatic cancer, and ovarian cancer." (PMID 33469538, 2020). "This suggests the development of other TLR4 agonists as adjuvants or drugs for cancer immunotherapy." (PMID 32765484, 2020). "TLR4-mediated inflammation is involved in several cancers and also in chronic diseases, having a pivotal role as amplifier of the inflammatory response." (PMID 32707760, 2020). "Clinical trials concerning TLR-4 signaling inhibition/promotion in many cancers are recruiting patients." (PMID 32354122, 2020). "Clinical trials contesting TLR-4 agonists and inhibitors are recruiting patients with various cancers." (PMID 32354122, 2020). "TRAF6-BECN1 signaling axis in TLR4 signal plays an essential role for the autophagy induction, thereby it regulates cancer migration and invasion." (PMID 33172060, 2020). "Collectively these results suggest that p62 negatively regulates autophagy activation, cancer cell migration and invasion induced by TLR4 stimulation." (PMID 32384667, 2020). "The TLR4/myeloid differentiation factor 88 (MyD88) pathway has been recognized as oncogenic signaling in human cancers and is correlated with patients’ poor survival." (PMID 33195243, 2020). "Mainly based on the mechanism, TLR4 agonists have immunomodulatory effects as adjuvants in vaccines, chronic viral infection therapy, and cancer therapy." (PMID 33469538, 2020). "Another important finding in the current study was that p62 regulated cancer cell invasiveness was facilitated by TLR4 stimulation through autophagy activation." (PMID 32384667, 2020). "In this study, we explained the anti-cancer effect of miR-365 in gastric precancerous lesions via regulation of the TLR4/IRF3/YAP/CDX2 axis." (PMID 33292210, 2020). "A recent study reported that TLR4-induced inflammation acted as a key promoter for cancer progression." (PMID 32158615, 2020). "Collectively, these results suggest that p62 is negatively implicated in the TRAF6-BECN1 signaling axis, thereby inhibiting cancer cell migration and invasion regulated by autophagy activation in response to TLR4 stimulation." (PMID 32384667, 2020). "TLR4, which is expressed in many human cancer cell lines, plays an important role in linking LPS to inflammation and cancer invasion and progression." (PMID 32492880, 2020). "Taken together, these results suggest that p62 negatively regulates autophagy activation, thereby functionally affecting cancer cell migration and invasion induced by TLR4." (PMID 32384667, 2020). "In the liver, TLR4 and TLR9 play essential roles in the liver inflammation–fibrosis–cancer axis, as TLR4–/– or TLR9–/–Tak1ΔHep mice experience reduced spontaneous HCC development compared to Tak1ΔHep mice." (PMID 33163393, 2020). "The pro-cancer mechanisms of TLR4 expressing on cancer cells include promoting an environment suitable for the continued proliferation of cancer cells and helping to evade cancer cells from immune surveillance." (PMID 33469538, 2020).
cancer (continued). "The complex and TLR4 synergistically induce the MyD88-dependent signaling pathways that lead to transcription factors, which promote inflammation and cancer." (PMID 33469538, 2020). "Nevertheless, a better understanding of the mechanism of action of TLR4 in cancer and in other diseases is necessary to develop potent and successful drug candidates." (PMID 32023919, 2020). "In p62 knockout cancer cells, stimulation of TLR4 induced activation of the TRAF6-BECN1-autophagy axis leads to cancer cell migration and invasion." (PMID 33324568, 2020). "Cancer cells are exposed to ER stress secrete unknown soluble factors, and these mediators can cause macrophages to initiate ER stress accompanied by transcriptional activation and pro-tumor proinflammatory cytokine secretion in a toll like receptor 4 (TLR4)-dependent manner." (PMID 33267910, 2020). "On the other hand, MMP2, which plays roles in degrading the ECM and promoting cell invasion, is also an important component of TLR4-driven cancer metastasis." (PMID 32367494, 2020). "TLR4 has been reported to overexpress in inflammatory sites and various cancer tissues through LPS exposure and the following NF-κB and MAPK pathway activation." (PMID 32448225, 2020). "Activation of toll-like receptor 4 (TLR4) induces an inflammatory signal that increases the tumorigenic potential of cancer cells and promotes their immune evasion, stimulating the release of more effective immunosuppressive exosomes." (PMID 33227947, 2020). "In the pathways in cancer, the expression of Wnt signalling was significantly decreased in the ApcMin/+ TLR4−/− mice gut tissue compared with the ApcMin/+ WT control." (PMID 31650683, 2020). "Evidence from recent studies suggests that enhanced expression of TLR4 in chronic infectious and inflammation are correlated with cancer progression." (PMID 32707760, 2020). "TLR4 is generally reported in immune cells but aberrant expression was found in various types of carcinoma, showing a correlation between its expression level and the malignancy of cancer." (PMID 32492880, 2020). "It is reasonable that both of TLR4 signals can induce liver inflammation, promote fibrosis, and aggravate progression toward malignancies in TLR4-dependent cancers such as HCC." (PMID 31068809, 2019). "Previous studies have reported that paclitaxel induced TLR4-mediated signaling in many cancer cells." (PMID 31156650, 2019). "Most importantly, TLRs can trigger a different response depending on the cell type (e.g., cancer cell or immune cell), and particularly, TLR4 has been reported to be a precursor of the immune escape of OC cells." (PMID 31861351, 2019). "The role of TLR4 in promoting maturation of antigen presenting cells and directing the induction of adaptive immune responses makes TLR4 agonists good vaccine adjuvants for use in infectious diseases or cancer." (PMID 31062071, 2019). "Prior studies illustrated that p38 represented a key biological downstream target of TLR4 in both acute/chronic inflammatory disease and cancers." (PMID 31507429, 2019). "Cancer cell-derived IgG regulates LPS-induced proinflammatory cytokine production by binding to TLR4 and enhancing TLR4 expression." (PMID 30692520, 2019). "Consistent with the previous report, TLR4 stimulation induces cancer migration and invasion through the autophagy activation." (PMID 31620128, 2019). "Using these human cancer cells, numerous ribosomal family proteins were found in pull-down assays conducted with recombinant TLR4." (PMID 30819254, 2019). "More interestingly, neutralizing antibodies of TLR2 and TLR4 significantly blocked NET-induced cancer cell migration, suggesting the involvement of TLR2 and TLR4." (PMID 31034495, 2019). "The consequences of Hb interacting with TLR4 is another potential anomaly, impacting cancer cell adaptation and survival." (PMID 31163699, 2019).
cancer (continued). "The aim of this study is to explore the immunosuppressive properties of cancer cell-derived exosomes released upon TLR4 activation by its direct ligand lipopolysaccharide (LPS)." (PMID 31186484, 2019). "Our study demonstrated that TLR4 and NF-κB expressions were elevated in LOM and OSCC, which displayed intimate clusters in a PCA plot; hence, TLR4 promoted cancer progression and possibly served as a prognostic factor." (PMID 31318878, 2019). "Following this, lysates from three cancer cells were used in pulled-down experiments with recombinant TLR4." (PMID 30819254, 2019). "HMGB1 is a multifunctional protein that promotes cancer progression and metastasis as a ligand of RAGE or TLR4 in various malignant tumors." (PMID 31905926, 2019). "Meanwhile, our results demonstrate that CRBN negatively regulates cancer migration and invasion through the inhibition of autophagy activation induced by TLR4 stimulation." (PMID 31620128, 2019). "The activation of the TLR4 pathway induces an inflammatory signaling that increase the tumorigenic potential of cancer cells and promotes their immune evasion." (PMID 31186484, 2019). "The TLR4 modulation holds promise for the treatment of various pathologies including immunological diseases, viral infections, cancers, and inflammation." (PMID 31480568, 2019). "In particular, paclitaxel is known to trigger the production of proinflammatory cytokines such as interleukin (IL)-6 and IL-8 via binding to Toll-like receptor 4 (TLR4) on myeloid cells and many cancer cells." (PMID 31156650, 2019). "Studies have shown that many BPTAs, specifically the TLR4 based agonists, can be used as immuno-therapeutic vaccines against cancer." (PMID 31191528, 2019). "As one of the most important pattern recognition receptors (PRRs), TLR4 draws more and more attention for its effect on cancer progression." (PMID 30957973, 2019). "The EV-based anticancer vaccine nanoparticle HDEA@EVAT was designed and developed by conjugating pH-sensitive DEAP, CD44 receptor-bound polysaccharide HA, TLR4-associated MPLA, and cancer-involved antigen MUC1." (PMID 30691225, 2019). "Taken together, our findings identify MGLL as a switch for CB2/TLR4-dependent macrophage activation and provide potential targets for cancer therapy." (PMID 29968710, 2018). "TLR4 is overexpressed in macrophages and cancer cells, including colon cancer cells, lung cancer cells, and melanoma cells." (PMID 29338742, 2018). "Further studies are needed to determine the mechanism involved for the contradictory effects of TLR4 on cancer." (PMID 29928275, 2018). "Studies have also suggested TLR4 to promote angiogenesis in different cancers by activating the PI3K-AKT signaling pathway to induce VEGF expression." (PMID 29342159, 2018). "The aim of the present review is to describe the role of the TLR4 signaling pathway between inflammatory response and cancer progression." (PMID 30213077, 2018). "Eighty-four of 182 cancers (46.2%) had high expression (cut-off value ≥ 197) of PAUF, and 91 of 182 cancers (50.0%) had high expression (cut-off value ≥ 135) of TLR4." (PMID 30111860, 2018). "It is thus proposed that during PTX elimination of cancer cells, it activates inflammatory mediators, in particular IL-6, IL-8 and XIAP from cancer cells, and these cytokines can then aggravate anti-apoptosis via the TLR4 signaling pathway." (PMID 29486738, 2018). "Particularly, TLR4 has been recognized as a key element in promoting the immune evasion of many cancer cells, including OC cells." (PMID 29343281, 2018). "TLR4, an inflammatory factor receptor, has been reported to play a significant role in various cancers." (PMID 29602239, 2018). "Recent approaches into the understanding of its mechanism of action showed that P-MAPA efficiently modulated TLR2 and TLR4 in both cancer and infectious diseases, besides stimulating T cells (TCD4+ and TCD8+ cells) and natural killer (NK) cell responses." (PMID 29343281, 2018).
cancer (continued). "The role of the TLR4 pathway in AT remodeling during cancer cachexia development remains unexplored." (PMID 30575787, 2018). "HMGB1 induces an antitumor response by binding the Toll-like receptor 4 (TLR4), activating dendritic cells, killing cancer cells, and inhibiting metastasis." (PMID 30486451, 2018). "CD19, CDKN1A, and TLR4 have also been reported to influence therapeutic resistance or overall prognosis in cancer." (PMID 29342159, 2018). "We searched PubMed, Embase and the Cochrane Library (last update by April 18, 2017) to identify literatures evaluating the value of TLR4 in cancer patients." (PMID 29560134, 2018). "The impact of CpdA to PTX resistance of the two cancer cells through TLR4 mediated production of these cytokines was demonstrated." (PMID 29486738, 2018). "TLR4 promotes cancer progression by activating several signaling pathways, but M2-CM specifically activated the STAT3 signaling pathway in the present study." (PMID 29338742, 2018). "In one study, autophagic CAFs in luminal breast cancer induced stemness in the cancer cells through the secretion of high-mobility group box 1 (HMGB1), resulting in the activation of toll-like receptor 4 in the cancer cells." (PMID 30380628, 2018). "Because TLRs, especially TLR2 and TLR4, are implicated in the pathogenesis of OC, compounds displaying either agonist or antagonist activities may represent a potential immunotherapeutic opportunity for cancer treatment, whether used alone or in combination with other therapies." (PMID 29343281, 2018). "The activation of TLR4 of immune cells and their impact on cancer cell death has been well documented." (PMID 29983866, 2018). "On the other hand, the inhibition of TLR4 limited cancer progression, while the inhibition of the TLR adapter protein myeloid differentiation primary response gene 88 (MyD88) unpredictably worsened pancreatic inflammation and cancer development." (PMID 29563853, 2018). "In line with this, it has been recently described that cancer stem cells isolated from patient-derived GBM xenografts showed a gradual increase in the expression of TLR4 under differentiation conditions." (PMID 29679017, 2018). "The detection of higher frequencies of the TLR2, TLR4 and/or TLR9 polymorphisms in CRC patients compared with the control groups highlight the role of these polymorphism in CRC development and cancer progression." (PMID 29883450, 2018). "Many pharmaceutical companies are developing TLR4 antagonists or agonists for the treatment of cancers and inflammatory diseases." (PMID 30213077, 2018). "It is consistent to the previous studies that stimulation of the TLR4 signaling pathway sustained chemoresistance and cancer progression." (PMID 29486738, 2018). "In this review, we will discuss the different functions of TLR4 in cancer progression and inflammation." (PMID 30213077, 2018). "TLR-4/NF-κB dependent pathway can be activated by PTX to promote the survived cancer cells to produce pro-inflammatory cytokines, some of which can stimulate cancer aggressiveness." (PMID 29486738, 2018). "For example, the interaction of lipopolysaccharide (LPS) with Toll-like receptor 4 (TLR-4) on KCs showed stimulation of cancer-promoting signaling pathways in mice." (PMID 30410942, 2018). "We found a statistically significant trend for increasing TLR4 expression from normal mucosa to gastric cardia inflammation and carcinoma (P < 0.05)." (PMID 29670922, 2018). "TLR4 expression gradually increased from normal mucosa to gastric cardia inflammation and carcinoma, thereby providing pathological evidence that TLR4 expression is involved in GCC inflammation and carcinogenesis." (PMID 29670922, 2018). "In addition to cancer cachexia, TLR4 may mediate cachexia associated with other diseases." (PMID 28536426, 2017). "TLR4 signaling plays a crucial role in the generation of innate response but also serves to activate the adaptive immune system in response to cancer." (PMID 28408791, 2017).